LRRIQ4 (leucine rich repeats and IQ motif containing 4)
Synonyms: LRRC64
Tractability: No criterion of Open Targets' tractability assessment is met for any kind of drug.
Gene: Protein-coding gene on chromosome 3 (169,812,870 to 169,837,773, forward strand). Ensembl gene ENSG00000188306.
Subcellular location (Human Protein Atlas): Mitochondria
Gene Ontology:
Cellular component: cytoplasm
Genetic constraint (gnomAD): Loss-of-function variants: 25 observed, 45.07 expected, observed/expected ratio (o/e) 0.55, 90% interval 0.4 to 0.77. The upper end of that interval is the gene's LOEUF score, 0.77, which puts it in group 3 of 6, group 1 being the genes least tolerant of losing a copy. Missense variants: 655 observed, 685.38 expected, observed/expected ratio (o/e) 0.96, 90% interval 0.9 to 1.02. Synonymous variants: 277 observed, 292.06 expected, observed/expected ratio (o/e) 0.95, 90% interval 0.86 to 1.05.
Homologues: Orthologues: chimpanzee LRRIQ4 (99% identical), macaque LRRIQ4 (96% identical), pig LRRIQ4 (75% identical), rabbit LRRIQ4 (72% identical), guinea pig LRRIQ4 (72% identical), dog LRRIQ4 (72% identical), mouse Lrriq4 (69% identical), rat Lrriq4 (69% identical). Paralogues in human: SCRIB (28% identical), ERBIN (25% identical), LRRD1 (25% identical), LRRC7 (25% identical), MFHAS1 (24% identical), PHLPP2 (24% identical), PHLPP1 (24% identical), SHOC2 (23% identical), LRRC1 (23% identical), PIDD1 (21% identical), LRRC40 (21% identical), LRRC8A (21% identical), and 19 more.